ACSL4 (acyl-CoA synthetase long chain family member 4)
Diseases named in the same sentence as ACSL4 in open-access papers (continued):
Sharing a sentence is not in itself a finding about the gene and the disease.
colorectal cancer (continued). "High expression of ACSL4 predicted a worse prognosis in colorectal cancer, but predicted better prognosis in breast, brain and lung cancer." (PMID 27171439, 2016). "Analysis from the Oncomine indicated that ACSL4 was down-regulated in bladder, brain, breast, leukemia, and lung cancer, but up-regulated in colorectal cancer, head and neck, kidney, myeloma, and liver cancer." (PMID 27171439, 2016). "Combination of the gene expression from Oncomine and survival from PrognoScan revealed the oncogenic role of ACSL4 in colorectal cancer and the tumor suppressor role of ACSL4 in breast, brain, and lung cancer." (PMID 27171439, 2016). "In addition, CYP1B1 has been shown to decrease the efficacy of anti-PD-1 therapy in colorectal cancer by preventing ferroptosis through the degradation of ACSL4." (PMID 40435846, 2025). "In colorectal cancer, coactivator-associated arginine methyltransferase CARM1 methylates arginine 339 (R339) of ACSL4, promotes the binding of RNF25 to ACSL4 and its ubiquitination, inhibits ferroptosis of tumor cells, and effectively attenuates ferroptosis-related cancer immunotherapy." (PMID 40050614, 2025). "Studies have shown that Apatinib can regulate the expression of ACSL4 in colorectal cancer cells." (PMID 38370339, 2024). "Here, we focus on the potential roles of ACSL4 in colorectal cancer." (PMID 35910359, 2022). "Systematic analysis and in vitro experiment confirmed that high expression of ACSL4 predicted a worse prognosis in colorectal cancer and downregulating ACSL4 could reduce cell proliferation and invasion." (PMID 35910359, 2022). "These highly similar compounds may contribute to the treatment of cancers with elevated ACSL4 expression, including colorectal cancer and liver cancer." (PMID 35126480, 2022). "Together, these findings imply the oncogenic property of ACSL4 in colon cancers, with 30–40% of the tumors carrying a KRAS mutation, in which KRAS G12V mutation is one of the major pathologic features of SW480 as a colorectal cancer cell line." (PMID 33466836, 2021). "However, overexpression of either ACSL1 or ACSL4 in colorectal cancer cells is sufficient to increase wound healing, cell invasion and proliferation compared to empty vector control cells." (PMID 31344914, 2019). "Specific ACSL4 knockdown shows a reduced colorectal cancer cell proliferation." (PMID 31344914, 2019). "Similar to ACSL1, ACSL4 is shown to have the potential for colorectal carcinoma treatment." (PMID 31344914, 2019). "Apatinib might also enhance ELOVL6/ACSL4-mediated ferroptosis in colorectal cancer cells." (PMID 38347631, 2024). "The expression of ACSL4 was significantly upregulated while the expression of GADD45B was significantly downregulated in the HCC tumor tissues compared to matched normal tissues or histologically normal liver tissues from colorectal cancer patients who had liver metastases." (PMID 28900541, 2017). "Apatinib reduces the expression of GPX4 and upregulates the expression of ACSL4 and ECOVL6 to promote ferroptosis in colorectal cancer cells." (PMID 40721409, 2025). "CPT1A can downregulate ACSL4 expression and the downregulation of ACSL4 has been found to mediate ferroptosis‐related resistance to sorafenib in HCC or oxaliplatin in colorectal cancer (CRC)." (PMID 40919131, 2025). "A report indicates that ACSL4 is methylated at the R339 site through ADMA modification by CARM1, which suppresses ferroptosis in colorectal cancer cells." (PMID 40756764, 2025). "In one study, 3,5-di-CQA was shown to suppress mitochondrial dysfunction and ferroptosis by regulating the expression of GPX4, ACSL4, and SLC7A11 in colorectal cancer cells." (PMID 39754271, 2025). "In colorectal cancer, the inhibitory effect of emodin on VEGFA achieved through targeting long-chain acyl-CoA synthetase 4 (ACSL4)." (PMID 38687357, 2024). "Three main ACSL isoforms have been found to be upregulated in colorectal cancer, ACSL1, ACSL4 and ACSL6." (PMID 31344914, 2019).
colorectal cancer (continued). "ACSL4 maintains a flexible role as a suppressor or an oncogene in different cancers, ACSL5 physiologically acts as a tumor suppressor in cancers, and ASCL6 is downregulated in diverse kinds of cancers, in addition to colorectal cancer." (PMID 35186949, 2021). "On the other hand, the inhibition of ACSL4 with a non-toxic dose of Triacsin C does not have a significant impact on the cell viability of colorectal cancer cell lines." (PMID 31344914, 2019). "As suggested by Cruz-Gill and colleagues, the inhibitory effect of miR-19b-1 on ACSL1, ACSL4 and SCD1 in colorectal carcinoma could be exploited as a therapeutic strategy." (PMID 31344914, 2019). "Specific shRNA knockout of ACSL4 could inhibit erastin-induced ferroptosis in KRAS mutant DLD-1 cells, indicating that ACSL4 was a key regulatory molecule for bromelain to effectively inhibit KRAS mutant colorectal cancer by stimulating ferroptosis." (PMID 35910359, 2022). "Moreover, our preliminary immunohistochemical staining showed that the expression intensity of both ACSL4 and GPX4 was higher in colorectal cancer tissues than in paracancerous tissues, which also suggested that ferroptosis might have a regulatory role in colorectal cancer." (PMID 37207153, 2023). "Another interesting relationship between colorectal cancer and ACSLs involves the regulation of ACSL1 and ACSL4 by non-canonical micro-RNAs (miRNAs)." (PMID 31344914, 2019).
prostate carcinoma (39 papers, 2015 to 2026). A carcinoma that arises from epithelial cells of the prostate gland. "The upregulation of ACSL4 is associated with an advanced stage of prostate cancer and is also correlated with tumor invasion and migration in prostate cancer cells." (PMID 39335604, 2024). "Iron accumulation does also cause oxidative stress, then inducing lipid peroxidation in prostate cancer lipid rich-cells, known to over-express ACSL4." (PMID 36829917, 2023). "Our data establish the RB/E2F/ACSL4 axis as a rheostat of ferroptosis that can be exploited for the treatment of RB1 loss–driven prostate cancer." (PMID 36928314, 2023). "A similar scenario exists for prostate cancer where increased ACSL4 is associated with increased aggressiveness, therapeutic resistance and enhanced anti-apoptotic signalling." (PMID 32286604, 2020). "In this prospective observational study, our objective was to investigate the serum levels of Acyl-CoA synthetase long-chain family member 4 (ACSL4) in prostate cancer (PCa) patients and examine its association with other serum biomarkers, and the clinical outcomes of PCa patients." (PMID 39465761, 2024). "Indeed, we observed that homozygous loss of RB1 correlates with higher expression of ACSL4 in the data sets of metastatic castration-resistant prostate cancer." (PMID 36928314, 2023). "Notably, ACSL4 (acyl-CoA synthetase long-chain family member 4) has emerged as a significant player, as its high expression has been linked to promoting prostate cancer growth, invasion, and hormonal resistance, thereby contributing to disease aggressiveness." (PMID 37860121, 2023). "This study uncovers a previously unrecognized mechanism by which palmitoylation regulates ferroptosis through modulating ACSL4 stability, and highlights the ZDHHC2‐USP19‐ACSL4 axis as a druggable target for overcoming resistance in advanced prostate cancer." (PMID 41126755, 2026). "ACSL4 promotes the malignant progression by upregulating the overall protein myristoylation in estrogen receptor (AR)-dependent prostate cancer cells." (PMID 40050614, 2025). "Specifically, our results revealed a significant elevation of the key ferroptosis biomarker ACSL4 in response to Enz treatment, suggesting that Enz can induce ferroptosis in prostate cancer." (PMID 40849495, 2025). "We conclude that Panobinostat’s inhibitory influence on prostate cancer growth and progression is mediated through the upregulation of LHPP, closely associated with the ferroptosis-related gene ACSL4." (PMID 39261475, 2024). "Regarding ACSL4, its knockdown has been associated with cisplatin, paclitaxel, and doxorubicin sensitivity in TNBC, and docetaxel sensitivity in prostate cancer." (PMID 39174500, 2024). "Concurrently, assessing the ubiquitination levels of ACSL4 in prostate cancer cells, we ascertained that SKP2’s overexpression markedly amplified ACSL4 ubiquitination in a dose-correlated manner." (PMID 39261475, 2024). "In conclusion, our findings suggest that LHPP regulates ACSL4 expression, thereby promoting ferroptosis in prostate cancer cells." (PMID 39261475, 2024). "Additional studies expand on a role for ACSL4 in promoting prostate cancer growth, invasion and hormone resistance, confirming an inverse relationship between ACSL4 expression and that of the androgen receptor." (PMID 37306503, 2023). "Similar results are observed in prostate cancer cells; and in colon cancer cells, ACSL4 has been shown to be part of a triad (ACL1/ACSL4/SCD) that induces EMT." (PMID 37306503, 2023). "We found that, similar to RB, depletion of RBL1 or RBL2 led to upregulation of ACSL4 and E2F-targeted genes and sensitized prostate cancer cells to ferroptosis induction." (PMID 36928314, 2023). "In prostate cancer, androgen receptors synergistically regulate the expression of ACSL3 and ACSL4, and knocking out ACSL4 inhibits the proliferation, migration, invasion, and xenograft growth of androgen receptor dependent prostate cancer cells." (PMID 37305043, 2023).
prostate carcinoma (continued). "Similar results have been reported for the relationship between AR and ACSL4 expression in prostate cancer." (PMID 37306503, 2023). "lncRNANEAT1 inhibits the expression of miR-34a-5p and miR-204-5p, regulates ACSL4 by sponging miR-34a-5p and miR-204-5p, promotes doxorubicin resistance in PCa cells, and accelerates the progression of prostate cancer." (PMID 35743814, 2022). "For example, ACSL4 contributes to de novo steroid synthesis, and chemical inhibition of ACSL4 was reported to reduce tumor growth in steroid-dependent models of breast and prostate cancer." (PMID 35963845, 2022). "For example, NEAT1 can promote prostate cancer by regulating ACSL4 via sponging miR-34a-5p and miR-204-5p, and promotes the growth of gastric cancer cells by regulating the miR-497-5p/PIK3R1 axis." (PMID 33738254, 2021). "Acyl-CoA synthetase long-chain family member 4 (ACSL4) is overexpressed in breast and prostate cancer." (PMID 33869039, 2021). "As an oncogene, NEAT1 promotes docetaxel resistance in prostate cancer by regulating acyl-CoA synthetase long chain family member 4 (ACSL4) via sponging miR-34a-5p and miR-204-5p." (PMID 33738254, 2021). "In summary, NEAT1 can enhance the expression of ACSL4 by sponging miR-34a-5p and miR-204-5p, thereby promoting docetaxel resistance in prostate cancer cells and accelerating the progression of prostate cancer." (PMID 34803512, 2021). "Expression of ACSL4 was particularly increased in castration-resistant prostate cancer, compared with hormone naive prostate cancer." (PMID 33255236, 2020). "NEAT1 also affects ACSL4 expression by competitively sponging both miR-34a-5p and miR-204-5p in prostate cancer." (PMID 33123488, 2020). "Up-regulated ACSL4 expression has been previously characterised in extrahepatic cancers such as colon adenocarcinoma, lung, breast and prostate cancers." (PMID 32286604, 2020). "The expression of ACSL4 mRNA is correlated with the estrogen receptor alpha expression and ACSL4 is sensitive to the triacsin C treatment, indicating that ACSL4 affects the steroid hormone-sensitivity in breast and prostate cancer." (PMID 27171439, 2016). "Moreover, we synthesized the specific enzymatic inhibitor of ZDHHC2‐TTZ1, and showed that TTZ1 restores ACSL4 levels, reinstates ferroptosis sensitivity, and overcomes enzalutamide resistance in prostate cancer." (PMID 41126755, 2026). "Furthermore, the prostate cancer tissue microarray revealed a positive correlation between the protein levels of ACSL4 and USP19." (PMID 41126755, 2026). "Moreover, assays for MDA and ROS indicated that RGFP966 only partially restored the capability of ACSL4 to promote lipid peroxidation and ferroptosis in prostate cancer cells." (PMID 39261475, 2024). "The deletion of ACSL4 gene confers resistance to ferroptosis in PC3 and DU145 cells, suggesting that ACSL4 gene expression level might be a proxy in predicting sensitivity to ferroptosis in prostate cancer cells." (PMID 36829917, 2023). "Given that RB-related proteins, RBL1 and RBL2, can functionally compensate for loss of RB in some settings, we investigated whether a similar RBL1/RBL2/E2F/ACSL4 axis exists in human prostate cancer." (PMID 36928314, 2023). "For example, NEAT1 can regulate the epigenetics of target gene promoters to play the role of oncogenes, by increasing ACSL4 via sponging miR-34a-5p and miR-204-5p, or HMGA2 via sponging miR-98-5p, and was found significantly associated with prostate cancer prognosis." (PMID 35075375, 2022). "And inhibitor targeting to ACSL4 could reduce prostate cancer growth, therapeutic resistance and steroidogenesis." (PMID 35910359, 2022). "Researchers found lncRNAs NEAT1 could promote docetaxel-resistant prostate cancer cells proliferation and invasion by sponging miR-204-5p and miR-34a-5p, leading to an increasing expression of ACSL4." (PMID 35910359, 2022).
prostate carcinoma (continued). "ACSL4, as well as ACSL3, which is an enzyme that converts fatty acids to acyl-CoA, is also involved in the loss of androgen sensitivity and acquisition of castration resistance, leading to cancer growth and invasion in prostate cancer." (PMID 33123488, 2020). "Notably, the lncRNA NEAT1 promotes docetaxel resistance in prostate cancer by regulating ACSL4 via sponging miR-34a-5p and miR-204-5p." (PMID 32889799, 2020). "However, homozygous loss of RBL1 or RBL2 was rarely observed in metastatic castration-resistant prostate cancer samples from various data sets, and no positive association was found between ACSL4 expression and inactivation of RBL1 or RBL2." (PMID 36928314, 2023). "Thus, the PGE2 that results from expression of ACSL4 activity might exert an autocrine effect on prostate cancer cells, interacting with surface receptors to activate PI3K/pAKT." (PMID 26636648, 2015). "Immunohistochemical (IHC) staining of a prostate cancer tissue microarray revealed a negative correlation between the protein levels of ACSL4 and ZDHHC2." (PMID 41126755, 2026). "LNCaP androgen-dependent prostate cancer cells, which do not express ACSL4, induce expression of ACSL4 when transformed into LNCaP-AI, which is androgen independent." (PMID 37306503, 2023). "Downregulation of ACSL4 significantly inhibits the non-AR dependent prostate cancer cells proliferation, migration and invasion." (PMID 35910359, 2022). "In addition, the target gene acyl coenzyme synthase 4 (ACSL4), another member of the ACSL family, is a downstream target of miR-34a-5p and miR-204-5p in prostate cancer." (PMID 35743814, 2022). "Upon initially treating cells with downregulated ACSL4 using both Panobinostat and RGFP966, we discovered that RGFP966 only partially restored the function of ACSL4 in curbing the proliferation of prostate cancer cells, unlike the significant restoration seen with Panobinostat." (PMID 39261475, 2024). "ACSL4 expression is increased in castration-resistant prostate cancer (CRPC) compared to that in hormone-naive prostate cancer and is involved in the development of tumor aggressiveness in prostate cancer through the regulation of various signal transduction pathways." (PMID 36497375, 2022).
ischemic stroke (34 papers, 2021 to 2026). A stroke disorder caused by obstruction of blood flow to the brain, due to thrombotic (local blood clot formation) or embolic (due to a blood clot or other material traveling from another site) event. "According to studies, the “Shugan Tiaoshen” acupuncture treatment effectively reduces the proteins and mRNA expression levels of LPCAT3 and ACSL4 in the brain tissue of ischemic stroke rats, resulting in neuroprotective effects." (PMID 40365351, 2025). "ACSL4 exacerbates ischemic stroke via two parallel mechanisms: triggering neuronal ferroptosis via lipid peroxidation and fueling neuroinflammation, the latter being evidenced by suppressed cytokine production upon its downregulation in microglia." (PMID 41306421, 2025). "ACSL4 promotes ischemic stroke injury by enhancing lipid peroxidation and neuroinflammation, making it a potential therapeutic target." (PMID 40880849, 2025). "In this study, these levels of ROS, MDA, GSH, iron and several ferroptosis‐related key proteins, such as GPX4, SLC7A11 and ACSL4, were detected in mice possessing ischemic stroke." (PMID 39233353, 2024). "ACSL4 expression is suppressed during the early stages of ischemic stroke, while overexpression of ACSL4 exacerbated ischemic brain injury." (PMID 38890797, 2024). "ACSL4 has been recently proved as a critical ferroptosis promoter in many non-tumor disease models, like organ intestinal/reperfusion, ischemic stroke, acute kidney injury, diabetic retinopathy, rhabdomyolysis, chronic prostatitis, and others." (PMID 37884942, 2023). "ACSL4 activation contributes to ferroptosis-induced brain injury and neuroinflammation in ischemic stroke." (PMID 36276334, 2022). "It has been shown that in ischemic stroke, ACSL4 is upregulated and mediates neuronal death, ultimately leading to stroke injury." (PMID 36425577, 2022). "Downregulation of ACSL4 has been found to be a novel treatment method for ischemic stroke by suppressing ferroptosis-induced brain damage." (PMID 35114894, 2022). "ACSL4 enhances ischemic stroke by inducing neuronal ferroptosis-related brain injury and neuroinflammation, while the inhibition of ACSL4 improves neurological functioning after stroke via the suppression of ferroptosis." (PMID 35805124, 2022). "Ischemia-induced ACSL4 activation can exacerbate ischemic stroke and contribute to ferroptosis-mediated tissue injury in ischemia/reperfusion." (PMID 36507355, 2022). "ACSL4 enhances ischemic stroke by increasing ferroptosis-induced brain damage and neuroinflammation while inhibiting ACSL4, which promotes the recovery of neurological function following stroke." (PMID 35264947, 2021). "Knockdown of ACSL4 has been reported to provide a new therapeutic approach for ischemic stroke by inhibiting ferromyopathy-induced brain damage and neuroinflammation." (PMID 34288826, 2021). "This overexpression of ACSL4 is possibly controlled by miR-347, which is increased after ischemic stroke and upregulates ACSL4 at the transcriptional or post-transcriptional level." (PMID 34149358, 2021). "Another study demonstrated that ACSL4 overexpression exacerbated ischemic stroke through strengthening cell ferroptosis-induced brain injury and neuroinflammation in mice." (PMID 34955860, 2021). "A clinical study indicated that the overexpression of ACSL4 may be regulated by miR-347, which is found to be elevated in patients with ischemic stroke, subsequently leading to the upregulation of ACSL4 expression." (PMID 40365351, 2025). "Intriguingly, HIF-1α induces the expression of ACSL4, a ferroptosis mediator, in ischemic stroke." (PMID 40653468, 2025). "For example, Hsp90 has been shown to facilitate the pathways of cellular death caused by oxidative damage and to activate Acyl-CoA synthetase long-chain family member 4 (ACSL4)—the factor permitting ferroptosis—driven by accumulation of lipid hydroperoxides in ischemic stroke." (PMID 39723236, 2024).